MYCLP1 (MYCL pseudogene 1)
Synonyms: formerly MYCL2; MYCL1P1
Gene: Processed pseudogene on chromosome X (107,272,582 to 107,273,656, forward strand). Ensembl gene ENSG00000204053.
Subcellular location: Nucleus
Diseases named in the same sentence as MYCLP1 in open-access papers:
MYCLP1 is named in the same sentence as 2 diseases in open-access papers, as found by Europe PMC text mining. Sharing a sentence is not in itself a finding about the gene and the disease.
MYCLP1 shares sentences with these, for which no sentence is quoted: breast carcinoma (1 paper); tumor (1).